CXCR4 (C-X-C motif chemokine receptor 4)
Diseases named in the same sentence as CXCR4 in open-access papers (continued):
Sharing a sentence is not in itself a finding about the gene and the disease.
hematological cancers (18 papers, 2014 to 2024). "The overexpression of the chemokine receptor 4 (CXCR4) in different epithelial, mesenchymal, and hematopoietic cancers makes CXCR4 an attractive diagnostic and therapeutic target." (PMID 27112767, 2016). "Additional support for its development as a nanomedicine for CXCR4+ EC comes from our previous work reporting a similar biodistribution of T22-GFP-H6 in other solid tumors or hematological cancers." (PMID 35884987, 2022). "Nevertheless, little is known about physiological mechanisms counteracting CXCR4 signaling in hematopoietic neoplasms." (PMID 33669329, 2021). "CXCR4 is expressed on solid and hematologic cancers including AML and has been demonstrated to be present in a complex with CCR5 on the cell surface." (PMID 31955503, 2020). "To assess the role of FtH on CXCR4 signaling in hematological tumors, we first measured CXCR4 levels in K562shFtH and in K562shRNA and we found that FtH knock down significantly enhanced CXCR4 expression at both mRNA and protein levels." (PMID 32432042, 2020). "Here, we designed the first anti-CXCR4 ADC with favourable therapeutic index, effective in xenografts of haematopoietic cancers resistant to standard of care and anti-CXCR4 antibodies." (PMID 30792442, 2019). "The CXCR4/SDF-1 axis is indeed important for hematological tumor cell survival, migration and interaction with their protective microenvironment." (PMID 29844860, 2018). "Since caspase activation and nuclear fragmentation are hallmarks of apoptosis, these results confirmed that LY2624587 indeed induced apoptosis of hematological tumor cells expressing high levels of CXCR4." (PMID 26954567, 2016). "Our study also demonstrated that LY2624587-induced apoptosis occurred only in hematologic tumor cells with high level CXCR4 expression." (PMID 26954567, 2016). "The most clinically advanced CXCR4-targeting radiopharmaceuticals are the [68Ga]Ga-PentixaFor/[177Lu]Lu-PentixaTher theranostic analogues, initially developed for CXCR4-targeted imaging and treatment in hematological cancers, and now tested in several solid tumours." (PMID 39008219, 2024). "CXCR4-targeted radioligand therapy (RLT) with [177Lu]Lu/[90Y]Y-PentixaTher has recently evolved as a promising therapeutic option for patients with advanced hematological cancers." (PMID 37162652, 2023). "In a first proof-of-concept human application in a group of five patients with hematological cancers, [99mTc]Tc-PentixaTec was well tolerated, allowed high-contrast delineation of CXCR4 expressing tumors, and exhibited a favorable overall biodistribution and dosimetry profile." (PMID 37597009, 2023). "Although many hematological tumor cell lines have been reported to express high levels of surface CXCR4, our flow cytometry analysis showed that multiple adherent solid tumor cell lines expressed low levels of surface CXCR4 (adherent)." (PMID 25514788, 2014). "CXCR4-targeted molecular imaging has been extensively evaluated across different hematologic and solid neoplasms, and the results indicate that 68Ga-pentixafor may emerge as a novel pan-hematologic tumor agent." (PMID 37290799, 2023). "CXCR4 and SDF-1 axis is important for hematological tumor cell survival, migration and interaction with their protective microenvironment." (PMID 26954567, 2016). "Sensitivity to ADC 513 did not correlate with CXCR4 cell surface density and ADC 513 caused cytotoxicity in all haematological tumour models with detectable CXCR4 surface expression." (PMID 30792442, 2019). "Cellular analysis showed LY2624587 antibody, but not LY2510924 peptide, down-regulated cell surface CXCR4 and induced hematological tumor cell death; both agents have been shown to inhibit SDF-1/CXCR4 interaction and downstream signaling." (PMID 29212254, 2017).
hematological cancers (continued). "Due to increased expression of CD184/CXCR4 and CD38, RPCI-WM1 represents a valuable model in which to study the effects anti-CXCR4 or anti-CD38 targeted therapies that are actively being developed for treatment of hematologic cancers." (PMID 25853860, 2015). "LY2624587 potently blocks SDF-1 binding to CXCR4, inhibits SDF-1/CXCR4 mediated cell signaling including ERK and AKT activation, induces cell surface receptor internalization, and induces dose-dependent cell death in vitro and in vivo in human hematologic cancer cells." (PMID 29212254, 2017).
neurodegenerative disease (18 papers, 2012 to 2025). A disorder of the central nervous system characterized by gradual and progressive loss of neural tissue and neurologic function. "CXCR4, a chemokine receptor implicated in microglial responses to neurodegenerative diseases, was upregulated in AD in our meta‐analysis as well as three other frontal lobe studies." (PMID 40042520, 2025). "We found that CXCR4 and functionally associated genes exhibit altered expression across a number of neurodegenerative diseases." (PMID 29636460, 2018). "In conclusion, by integrating large neurodegenerative GWAS data with gene expression data from neurodegenerative diseases and transgenic mouse models, our multi-modal findings indicate that CXCR4 is associated with PSP and PD neurodegeneration." (PMID 29636460, 2018). "Dysregulation of CXCR4 has been associated with neurodegenerative diseases." (PMID 31068785, 2019). "Thus, our data suggest that expression of CXCR4 and functionally associated genes are significantly altered in regions of the brain susceptible to different forms of neurodegenerative disease pathology." (PMID 29636460, 2018). "Dysregulation in the expression of the chemokine receptor CXCR4 has been demonstrated in a number of neurodegenerative diseases, including AD and PD, particularly in brain regions associated with pathology." (PMID 33126586, 2020). "Several studies have demonstrated that there is a powerful correlation between the dysregulated CXCR4 and neurodegenerative diseases including AD, and the inhibition of CXCR4/CXCL12 signaling pathways is able to alleviate glutamate release mediated toxic cascade and neuronal apoptosis." (PMID 36569892, 2022). "CXCR4 has been previously investigated for its role in AD and other neurodegenerative diseases." (PMID 31068785, 2019). "Despite the lack of strong genetic association across these three neurodegenerative diseases, we found that CXCR4 expression was altered in brains that are pathologically confirmed for PSP, PD, and FTD." (PMID 29636460, 2018). "Given that PSP, PD, and FTD are neuropathologically characterized by degeneration in the midbrain, cerebellum, and (to a lesser extent) neocortical regions, our findings may suggest that subtle alterations of CXCR4 and MAPT may predispose to regionally specific brain degeneration in later life." (PMID 29636460, 2018).
breast (12 papers, 2005 to 2025). "Furthermore, spatial correlation analysis revealed that the MIF-CD74+CXCR4 signaling axis was implicated in the activation of malignant cells and macrophages and was markedly elevated in the malignant regions of colorectal liver metastases." (PMID 41502509, 2025). "These extrahepatic cells are recruited to the liver during chronic liver injury, inflammation, or malignancy, primarily through the C-X-C motif chemokine receptor 4/stromal-derived factor 1 alpha (CXCR4/SDF1α) axis." (PMID 41438763, 2025). "The correlation among CXCR4, β-catenin, and PPARδ expression was investigated in 75 human lung ADC tissues using immunohistochemical staining of tissue microarray." (PMID 33637678, 2021). "We investigated whether SDF-1 binding to CXCR4 induced β-catenin and PPARδ and caused EMT in lung ADC cells." (PMID 33637678, 2021). "However, all 8 cases of UM liver metastases were found to express high levels of CXCR4." (PMID 35145271, 2022). "Therefore, we examined the relationship between SDF-1/CXCR4 and β-catenin activation in lung ADCs." (PMID 33637678, 2021).
gastrointestinal tumors (12 papers, 2010 to 2025). "Expression of the 4 autophagy-related genes (SQSTM1, BIRC5, NRG3, and CXCR4) can accurately predict the prognosis of gastrointestinal tumors in Asian patients." (PMID 34484469, 2021). "The combined expression of CXCR12 and CXCR4 activates G protein signal kinase, promoting the development of gastrointestinal tumors." (PMID 34484469, 2021). "AMD3100 (Plerixafor) is a CXCR4 blocker tested for gastrointestinal tumors." (PMID 39050233, 2024). "However, two patients showed false-negative CXCR4 PET scans in our patient cohort and the diagnostic inferiority of CXCR4 PET in patients with (neuroendocrine) gastrointestinal neoplasms has been shown before by our study group." (PMID 38332341, 2024). "The importance of the SDF1-CXCR4 axis in angiogenesis is apparent from the lack of gastrointestinal blood vessels in CXCR4−/− mice, and SDF1 has been shown to contribute to angiogenesis in gastrointestinal tumor models." (PMID 20087418, 2010).
bacterial infection (11 papers, 2012 to 2024). "Bacterial infections can stimulate early neutrophil release from the bone marrow via CXCR4 signaling." (PMID 33824337, 2021). "In this assay, we evaluated the possible roles of thereceptors CD74 and CXCR4 in the observed monocyte-endothelial cell adhesion.Bacterial infection has been previously observed to increase cell adhesion by8.17-fold." (PMID 30506423, 2019). "We further showed that systemic bacterial infection modulated the trafficking of both T lymphocytes and monocytes by activating the expression of both CXCR4 and CCR5." (PMID 26087960, 2015). "Various studies imply that neutrophil mobilization from the BM to peripheral organs in general, and the lung in particular during bacterial infections is also CXCR4-SDF-1-dependent." (PMID 23189271, 2012). "The addition of MSX-122 to the culture media during the bacterial infection significantly attenuated the amount of TNF-α induced by these strains, suggesting that CXCR4 plays crucial roles in the host response to the CD-isolated invasive E.coli." (PMID 22485156, 2012). "Interestingly, studies of WHIM (Warts, Hypogammaglobulinemia, recurrent bacterial Infections, and Myelokathexis) syndrome indicated that CXCR4 mutants, lacking the terminal 19 residues of the C-terminal tail which includes S339, do not have a decreased surface expression of the receptor." (PMID 39062849, 2024).
kidney diseases (11 papers, 2018 to 2026). "As the exclusive receptor for SDF-1, CXCR4 has been implicated as a crucial mediator of renal regeneration and kidney diseases." (PMID 39512693, 2024). "These pathways are altered in kidney disease and are linked to the production of vascular endothelial growth factor, erythropoietin, adiponectin, interleukin (IL)-18, IL-23, and chemokines that bind CXCR3, CXCR4, and/or CXCR7." (PMID 33676416, 2021). "To conclude, this study is the first to our knowledge to report that i-bodies targeting CXCR4 ameliorate kidney fibrosis in both FA and UUO models of kidney disease." (PMID 35015734, 2022). "Although some animal studies showed that DPP4i may suppress kidney oxidative stress and fibrosis through the SDF-1α/CXCR4-depdendent signaling pathway, the proinflammatory effects of SDF-1 can also exacerbate the progression of kidney disease." (PMID 41304709, 2025). "Rizzo's research has also revealed the close relationship between Ang II/AGTR1 and SDF-1α/CXCR4 in kidney diseases, indicating that increased Ang II could activate podocytes to release SDF-1α, which binds to its receptor CXCR4 located on parietal epithelial cells (PECs)." (PMID 31219799, 2019).
inflammation (9 papers, 2017 to 2023). Aberrant reaction of the microcirculation characterized by movement of fluid and leukocytes from the blood into extravascular tissues. "High expression of CXCR-4 in high-risk atheromatous lesions and precursor pre-atheromatous lesions makes [68Ga]Ga-pentixafor a viable tool for non-invasive imaging of arterial inflammation." (PMID 33287237, 2020). "In summary, our data revealed a previously uncharacterized role of the SDF-1 receptors CXCR4 and CXCR7 in activated platelets and PMNs during acute peritoneal inflammation." (PMID 34948374, 2021). "Recently, experimental data suggested protective effects of CXCR4 and CXCR7 antagonism during pulmonary inflammation and provided evidence for a link between the SDF-1-CXCR4/CXCR7 axis and adenosine receptor signaling." (PMID 34948374, 2021). "In conclusion, we determined the pivotal role of CXCR4- and CXCR7-inhibition in acute pulmonary inflammation, which depended on A2B-receptor signalling." (PMID 28542132, 2017). "Moreover, future studies may also use more leukocyte-specific radiotracers, such as the C-X-C motif chemokine receptor 4 targeting PET agent [68Ga]Pentixafor, which was found to be useful in the context of myocardial inflammation." (PMID 34829421, 2021).
neurological disorders (9 papers, 2007 to 2025). "In the drug feasibility evaluation, by investigating potential drug development targets for CD5, which exhibits robust associations with CP, a promising candidate for neurological disorder drug development, protein CXCR4, was identified." (PMID 40988181, 2025).
infectious disease (8 papers, 2011 to 2023). A disorder directly resulting from the presence and activity of a microbial, viral, or parasitic agent in humans. "Likewise, WHIM patients treated with a low dose of a CXCR4 antagonist also restore leukocyte numbers in peripheral blood and have reduced susceptibility to infectious diseases." (PMID 33324418, 2020). "Another such example includes C C-X-C motif chemokine receptor 4 (CXCR4) as a potential new drug target for infectious diseases." (PMID 30285606, 2018). "Imaging CXCR4 expression on infiltrating leukocytes might as well be used to track leukocytes that are involved in infectious diseases." (PMID 30105558, 2018). "In infectious disease CXCR4 is employed by the human immunodefiency virus (HIV) to gain entry to cells and in stem cell localization CXCR4 plays an important role for B-cell lymphopoiesis and bone marrow myelopoiesis." (PMID 21349176, 2011).
blood cancers (7 papers, 2020 to 2024). "The mobilization of cells from the bone marrow to the periphery has important implications in the treatment of blood cancers, as the mobilization of quiescent stem-like cells into the blood stream from their protective niches using CXCR4 antagonists should make them more susceptible to chemotherapy." (PMID 38612911, 2024). "CXCR4 ERT also caused desired bone marrow ablation and has therefore been incorporated in the therapeutic algorithm of advanced blood cancer patients (allogenic/autologous HSCT following CXCR4 ERT along with successful engraftment)." (PMID 35674738, 2022). "Hence, there is an urgent need to develop a new 18F-labeled CXCR4-targeted radiotracer endowing with high imaging contrast and CXCR4-specific accumulation both in solid tumors and hematologic neoplasms." (PMID 39431004, 2024). "CXCR4-directed [68Ga]PentixaFor and [177Lu]/[90Y]PentixaTher, however, meet the urgent need to provide this innovative treatment strategy to patients affected with advanced blood cancer." (PMID 35674738, 2022). "The CXCR4-targeted PET agent [68Ga]PentixaFor has been successfully applied to patients with solid and advanced blood cancers, demonstrating substantially increased radiotracer accumulation in ACC, SCLC, MM, MZL, MCL, or gastric MALT." (PMID 35674738, 2022).
benign tumors (6 papers, 2014 to 2023). "Our data suggest increased PH inhibition as a promising tool for a customized upregulation of SDF-1 and CXCR4 expression to attract reparative CXCR4+/CD11b+ cells to the ischemic heart associated with increased cardiac repair." (PMID 28550361, 2017). "In contrast to protein expression data for CXCR4 in ccRCC, limited evidence exists for benign renal tissue, papillary and chromophobe RCC, benign tumors and metastatic tissue." (PMID 36982302, 2023). "In accordance to our result, the only study that evaluated CXCR4 at protein level by IHC in FMC also showed weakly positive expression in epithelial cells of benign tumors and no detectable CXCR4 expression in normal mammary tissue." (PMID 30012106, 2018). "Of note, the ratio of M2-like CXCR4-EGFP+CD11b+/CD206+ cells to inflammatory M1-like CD11b+/CD86+ cells increased by 2.6-fold after DMOG-induced PH inhibition compared to infarcted control mice, suggesting an improved fine-tuning of reparative M2-like cells in the ischemic heart after 7 days." (PMID 28550361, 2017).
cardiac disease (5 papers, 2018 to 2022). "As a key modulator of inflammatory response, CXCR4 has been shown to play a critical role in the development of cardiac diseases." (PMID 35048778, 2022). "Here, we assessed the homing activation status of bone marrow cells (BMC) concerning the SDF-1 and CXCR4 expression in ischemic (IHD) and valvular (VHD) heart diseases." (PMID 29784000, 2018).
brain disease (4 papers, 2015 to 2025). "This is in line with studies that report CXCL12/CXCR4 signaling improves cognitive performance in other models of brain disease, suggesting our results may also inform CNS therapeutic strategies more broadly." (PMID 40335156, 2025). "This novel application of CXCR4/TRAIL-enriched exosomes in improving the efficacy of chemotherapy highlights a new perspective for establishing a synergistic protocol with anticancer agents to treat brain disease." (PMID 32850457, 2020).
peripheral neuropathy (4 papers, 2012 to 2024). A disorder affecting the peripheral nervous system. "GPCR coupled signaling, including MAPKs, PI3K, STAT3 and NF-κB pathways, are proposed to function in CXCR4 signaling, and these pathways are also activated in the lumbar spinal cord following peripheral neuropathy." (PMID 25119456, 2014). "We next asked whether well-known, pro-nociceptive receptors for HMGB1, such as TLR4, RAGE, and CXCR4, contributed to the oxaliplatin-induced peripheral neuropathy." (PMID 31666085, 2019). "Blockade of CXCR4 signaling by its antagonist AMD3100 also suppresses established mechanical allodynia in HIV-associated peripheral neuropathy and reverses heat hyperalgesia, but not mechanical allodynia, induced by chronic constriction injury of sciatic nerve (CCI)." (PMID 22998838, 2012). "The present study demonstrates the critical role of HMGB1 in the development and maintenance of oxaliplatin-induced peripheral neuropathy, which is mediated by RAGE, TLR4, and CXCR4." (PMID 31666085, 2019). "Currently, systematic (intraperitoneal) administration of CXCR4 antagonist, AMD3100, was demonstrated to have analgesic effects on opioid-induced hyperalgesia and neuropathic pain induced by peripheral neuropathy and by anti-AIDS therapy." (PMID 25119456, 2014).
inflammatory myopathy (2 papers, 2019 to 2022). "The abundance of CXCR4, a chemokine receptor for ligand SDF1 (CXCL12), indicates inflammatory myopathy conditions." (PMID 30678732, 2019). "Neither gene expression of CCR7 nor CXCR4 was elevated in ASyS or IMNM patients (an acute inflammatory myopathy serving as DC) compared to NDC, while CXCL12 expression was elevated in PL-7+ patients when compared to Jo-1+ patients." (PMID 35612662, 2022).
retinopathy (2 papers, 2011 to 2016). "Further investigation in CXCR4/CCR5 interaction with the HIV-1 envelope and the mitochondria pathway of HRCEC apoptosis may ultimately prove the specific mechanisms of HIV-1 related retinopathy." (PMID 22219640, 2011).
skeletal disease (2 papers, 2022 to 2025). "In recent years, studies have found that the SDF-1/CXCR4 axis plays a role in OA, RA and other skeletal diseases and is a potential therapeutic target for OA and RA." (PMID 36554439, 2022).
animal disease (1 paper, 2022). "For instance, CCR1, CCR7, or CXCR4 modification was found to enhance the migration of MSCs to the injured myocardium, secondary lymphoid organs, and infarcted myocardium, respectively, and to promote recovery in animal disease models." (PMID 35123561, 2022).